BCL2 (BCL2 apoptosis regulator)
Diseases named in the same sentence as BCL2 in open-access papers (continued):
Sharing a sentence is not in itself a finding about the gene and the disease.
leiomyoma (12 papers, 2008 to 2025). A well-circumscribed benign smooth muscle neoplasm characterized by the presence of spindle cells with cigar-shaped nuclei, interlacing fascicles, and a whorled pattern. "The antiapoptotic protein B-cell lymphoma-2 (Bcl-2) has been proposed as diagnostic biomarker to distinguish uLMS from leiomyoma in challenging cases." (PMID 35344084, 2023). "They supposed that Bcl-2 protein associated with progesterone is responsible for the growth of leiomyomas by preventing apoptotic cell death." (PMID 27491369, 2016). "Data were extracted to calculate odds ratio (OR) for the association of Bcl-2 with uLMS vs leiomyoma variants and smooth-muscle tumors of uncertain malignant potential (STUMP), and hazard ratio (HR) for overall survival; a p value < 0.05 was considered significant." (PMID 35344084, 2023). "However, the reliability of Bcl-2 loss in differentiating uLMS from leiomyoma variants and smooth-muscle tumors of uncertain malignant potential (STUMP) is less clear." (PMID 35344084, 2023). "Smooth muscle tumors such as leiomyoma and leiomyosarcomas show strong positivity for actin and desmin and negativity for S100, BCL2, and CD34." (PMID 34211794, 2021). "Loss of Bcl-2 immunohistochemical expression does not appear able to differentiate uLMS from leiomyoma variants and STUMP, resulting therefore not useful as a diagnostic marker." (PMID 35344084, 2023). "This study showed that a loss of Bcl-2 immunohistochemical expression was significantly associated with shorter overall survival in uLMS, while it was not able to differentiate uLMS from leiomyoma variants and STUMP." (PMID 35344084, 2023). "The mechanism of action GBH may be similar to that of UPA, which inhibits the proliferation of leiomyoma cells and induces apoptosis by increasing cleaved-caspase-3 expression and decreasing Bcl-2 expression." (PMID 31607930, 2019). "BCL-2 levels were detected to be significantly higher in leiomyoma tissue in comparison to the normal myometrium and this may be correlated to the increased estrogen receptor levels in leiomyomas." (PMID 38085363, 2023). "Similarly, IGF may increase cellular proliferation in uterine leiomyoma cells through activation of the MAPK pathway and thus play a crucial role in leiomyoma cell growth, by upregulation of Bcl-2 protein expression in leiomyoma cells." (PMID 24163697, 2013). "Our results do not mean that the expression of Bcl-2 is the same between uLMS, STUMP and leiomyoma variants." (PMID 35344084, 2023). "These smooth muscle cells were negative to slightly positive for Bcl-2 (monoclonal, #124; DakoCytomation, Glostrup, Denmark) by immunohistochemistry, similar to that observed in tumor-free myometrium, whereas Bcl-2 expression was abundant in leiomyoma cells." (PMID 27491369, 2016).
autism (11 papers, 2011 to 2025). Persistent deficits in social interaction and communication and interaction as well as a markedly restricted repertoire of activity and interest as well as repetitive patterns of behavior. "Western blot analysis was used to investigate the hippocampal mean protein levels of Bax and Bcl‐2 in a VPA‐induced model of autism." (PMID 37596045, 2023). "Individuals with autism and bipolar have been found to have decreased levels of Bcl2 protein in the frontal cortex compared to controls." (PMID 24423034, 2014). "In the same year, another study focused on the comparison of RELN and Bcl-2 levels in homogenates of cerebellar tissue obtained from 5 subjects with autism and 8 controls, which showed a significant decrease of Reelin (43–44%) and Bcl-2 (34–51%) levels in comparison to healthy controls." (PMID 35422848, 2022). "The down-regulation of BDNF-Akt-Bcl2 anti-apoptotic signaling pathway could be responsible for pathogenesis of autism." (PMID 27917343, 2016). "Treatment with decitabine was shown to demethylate promoters and restore/induce the expression of the silenced RORA and BCL2 in autistic and patients with fragile X syndrome and hence, the use of DNA demethylating agents in drug therapy for autism and fragile X syndrome has been suggested." (PMID 24238559, 2013). "Their experiments showed that deregulation of Bcl-2 may result in some of the structural brain and behavioural abnormalities in patients with autism." (PMID 22937244, 2011). "BCL‐2 is expressed at lower levels in autism, although we do not know how the Leu206Met and His213Gln mutations may affect BCL‐2 IRES‐mediated translation, this could provide a potential explanation for how RPL10‐specialized ribosomes are linked to autism." (PMID 33565275, 2021). "As Bcl-2 works as an antiapoptotic agent mainly at the level of mitochondria, we may propose that its downregulation is one of the mechanisms related to increase of oxidative stress and mitochondrial dysfunction in autism." (PMID 22937244, 2011). "Indeed, a recent study has found decreased BDNF levels in the brains of autistic patients as compared to controls and has suggested this may lead to reduced BDNF-Akt-Bcl2 anti-apoptotic signaling in autism." (PMID 21731612, 2011). "We found Bcl-2, cytokines, MCP-1, oxidative stress, and other meaningful terms linking the literature on autism with the literature on NF-kappaB." (PMID 22937244, 2011).
B-cell neoplasm (11 papers, 2013 to 2025). A group of heterogeneous lymphoid tumors generally expressing one or more B-cell antigens or representing malignant transformations of B-lymphocytes. "In our cohort, SBS9 was observed in 4 cases: 2 low hypodiploid cases, 1 IGH::CEBPB and 1 IGK::BCL2 case with the highest mutation burden (42%), which we had expected, given the association of this lesion with mature B-cell neoplasms." (PMID 36867579, 2023). "To determine the effect of tumorigenesis caused by loss of TFL in matured B cell neoplasms, we utilized vavP-Bcl2 transgenic (Bcl2-Tg) mice as FL-bearing mice." (PMID 37304286, 2023). "For these experiments we used lymphocytes from mice representing three of the most characteristic of the B cell neoplasms developed by the TRAF3/BCL2 double-tg mice." (PMID 30687320, 2018). "It acts as an autocrine growth factor that upregulates BCL-2 expression in some cases of B-cell neoplasms." (PMID 28713071, 2018). "Altogether, these results indicate that TRAF3, perhaps by promoting exacerbated B cell responses to certain antigens, and BCL2, presumably by supporting survival of these clones, cooperate to induce mature B cell neoplasms in transgenic mice." (PMID 30687320, 2018). "FACS and immunohistochemical analyses show that different types of mature B cell neoplasms arise in TRAF3/BCL2 double-transgenic (tg) mice, all of which are characterized by the loss of surface IgM and IgD expression." (PMID 30687320, 2018). "As shown in this report, lymphoid-specific TRAF3/BCL2 double-tg mice develop B cell neoplasms, mostly DLBCL and plasma cell neoplasia, with high incidence (approximately 80% of the mice)." (PMID 30687320, 2018). "TRAF3/BCL2 +/+ B cell neoplasms can be transferred to and survive in immunodeficient mice." (PMID 30687320, 2018).
bipolar disorder (11 papers, 2012 to 2026). A disorder of the brain that causes unusual shifts in mood, energy, activity levels and the ability to carry out day-to-day tasks. "The Bcl-2 AA genotype has been associated with a reduced level of Bcl-2, whereas lower Bcl-2 protein and mRNA levels have been reported in the frontal cortex in bipolar disorders." (PMID 29422088, 2018). "However, both studies showed that the Bcl-2 polymorphism was associated with intracellular calcium homeostasis in lymphoblast cells derived from bipolar disorder patients." (PMID 23437205, 2013). "Lithium treatment increased ratio of anti-apoptotic to pro-apoptotic BCL-2 gene family members in lithium responders patients with bipolar disorder." (PMID 26074776, 2015). "Because the Bcl-2 genotypes have been reported to influence psychiatric presentation in bipolar disorders, we also included Neuropsychiatric Inventory (NPI) scores to evaluate whether the genotype groups affected the behavioral presentations." (PMID 29422088, 2018). "In bipolar disorder, a link between the anterior cingulate cortex, one of the key hubs in the salience network, and the salience network and Bcl-2 protein expression may exist." (PMID 29422088, 2018). "In bipolar disorders, lower Bcl-2 protein and mRNA levels have been reported in the frontal cortex." (PMID 29422088, 2018). "Previous studies have observed that higher Bcl-2 expression may protect against dysfunctional calcium homeostasis in bipolar disorder patients." (PMID 23437205, 2013). "However, most studies have focused on assessing the effects of lithium in neurons, ignoring examination of bcl-2 in astrocytes, which also influence neuronal survival and are affected in bipolar disorder." (PMID 24174697, 2013). "Furthermore, the addition of a clinical control group with a psychiatric disorder, such as bipolar disorder, to future study designs may yield added knowledge of the dual role of Bcl-2 in aging and disease states." (PMID 23437205, 2013).
Ewing sarcoma (11 papers, 2011 to 2026). A small round cell tumor that lacks morphologic, immunohistochemical, and electron microscopic evidence of neuroectodermal differentiation. "MRX-2843 is even more effective against Ewing sarcoma cells when combined with other drugs, venetoclax or navitoclax, that target a protein called BCL-2." (PMID 39199601, 2024). "For Ewing sarcoma (ES), BCL-2 and BCL-XL are simultaneously required to maintain cell survival, and monotherapy with venetoclax is not sufficient to sensitize ES cells to olaparib." (PMID 37894324, 2023). "Cell death occurs after mitotic arrest and is characterized by the inactivation of anti-apoptotic Bcl-2 proteins and by the activation of Bax in Ewing sarcoma cell lines, where caspases contribute only partially." (PMID 36614121, 2022). "Most of the in vitro studies using 4-HPR reported its anti-tumor activity due to induction of apoptosis with increased Bax : Bcl-2 ratio and caspase-3 activation in glioblastoma and also Ewing’s sarcoma cells." (PMID 21822457, 2011). "In both Ewing’s sarcoma SK-N-MC and RD-ES xenografts, there were significant increases in Bax : Bcl-2 ratio." (PMID 21822457, 2011). "Western blotting showed alterations in the expression of Bax and Bcl-2 proteins in Ewing’s sarcoma SK-N-MC and RD-ES xenografts." (PMID 21822457, 2011). "The concurrent upregulation of Bax and downregulation of Bcl-2 shifted the Bax/Bcl-2 ratio significantly in favor of apoptosis, thereby reinforcing the role of AVN944 in promoting programmed cell death in SK-ES-1 Ewing's sarcoma cells." (PMID 41522344, 2026). "The resulting increase in the Bax/Bcl-2 ratio favors apoptosis, suggesting that AVN944 shifts the balance towards a pro-apoptotic state in TC71 Ewing's sarcoma cells." (PMID 41522344, 2026). "For example, another article reported a case of Ewing sarcoma of the scapula that was positive for CD99, vimentin, and bcl-2." (PMID 39588414, 2024). "SOX2 advanced Ewing’s sarcoma cell survival and proliferation by regulating p21, p27 and cyclin-E to facilitate G1/S phase transition and mediating caspase-3, PARP via both extrinsic (Fas and caspase-8) and intrinsic (caspase-9, Bad, Bcl-2 and XIAP) apoptotic pathways to restrain cell apoptotsis." (PMID 26969300, 2016).
Hepatic steatosis (11 papers, 2020 to 2024). Steatosis is a term used to denote lipid accumulation within hepatocytes. "Parameters inherent to body mass, glucose tolerance, evaluation of liver enzymes, percentage of hepatic steatosis, oxidative stress, the process of cell death with the apoptotic biomarkers (Bax, Bcl2, and Cytochrome C), and the ultrastructure of hepatocytes were analyzed." (PMID 38831961, 2024).
lymphopenia (11 papers, 2008 to 2025). Reduction in the number of lymphocytes. "This possibility has been strengthened by genetic and cellular studies of the lymphopenias and cell death associated with GIMAP5 and GIMAP1 deficiencies which cast doubt on the involvement of the BCL2-related apoptotic machinery in the lymphopenias." (PMID 29718959, 2018). "Bcl-2-deficient mice and mice lacking myeloid cell leukemia 1 (Mcl-1) in the hematopoietic system exhibit profound lymphopenia, whereas mice overexpressing a Bcl-2 transgene throughout the hematopoietic compartment show marked lymphadenopathy." (PMID 18275830, 2008). "We identified a specific CHIKV signature composed of 107 down-regulated genes that includes CX3CR1, BTLA, BCL2, GZMK and three genes that encode Fc receptor-like glycoproteins that could be related to the lymphopenia induced by CHIKV infection." (PMID 31211814, 2019). "Circulating IL-7 levels increase during periods of lymphopenia to maintain naïve T-cell homeostasis and support the thymic-independent peripheral expansion and maintenance of mature T cells because they upregulate bcl-2 protein that has antiapoptotic properties." (PMID 24971338, 2014). "Moreover, up-regulation of proapoptotic proteins (B-cell lymphoma-2 protein-BCL-2, C-X-C motif chemokine ligand 10- CXCL10, and C-C motif chemokine ligand 2- CCL2) as well as interleukin 6 (IL-6) were presented as molecular alterations associated with lymphopenia in patients with this infection." (PMID 37046564, 2023). "In vivo transferred T-cells up-regulate expression of Bcl-2, FoxO1, Eomes and Atg7, enhance the phosphorylation of pSTAT5 and ULK1 and activate the mitochondrial biogenesis via IL-15 signaling in lymphopenia." (PMID 27158441, 2016).
osteonecrosis (11 papers, 2014 to 2025). A none disease characterized by death of bone tissue due to a lack of blood supply. "PRP can prevent glucocorticoid-induced apoptosis in a rat model of osteonecrosis of the femoral head by promoting Bcl-2 expression." (PMID 39906617, 2025). "Collectively, the miR-148a-3p/SMURF1/SMAD7/BCL2 axis contributes to maintaining osteoblast viability and bone integrity, thereby alleviating osteonecrosis of the femoral head." (PMID 41511311, 2025). "SPION‐labelled human umbilical cord mesenchymal stem cells proved to be advantageous in osteonecrosis treatment by inhibiting apoptosis of bone cells through the Akt/Bcl‐2/Bad/Caspase‐3 signalling pathway." (PMID 39219020, 2024). "Several studies have shown that regulating the expression of Bcl-2 and inhibiting the expression of Bax through in vitro and in vivo experiments can prevent the death of bone cells and thus prevent osteonecrosis of the femoral head." (PMID 38384969, 2024). "The results revealed that the associated genes were involved in the BCL-2/BAX apoptotic pathway and the ROS/JNK/c-Jun signaling pathway, further highlighting the significant role of cell apoptosis in glucocorticoid-induced osteonecrosis of the femoral head." (PMID 38384969, 2024). "Bone-related diseases, such as osteonecrosis, can result from apoptosis, which can be prevented by anti-apoptotic strategies such as inhibiting caspases, PARP, and Bcl-2 and inducing the PKB/Akt pathway and IAP family of proteins." (PMID 37185334, 2023). "Furthermore, DEHP disrupts the apoptosis-related genes BCL2 and CASP3, promoting osteocyte death and contributing to the development of osteonecrosis." (PMID 41303381, 2025).
osteoporosis (11 papers, 2010 to 2026). A condition of reduced bone mass, with decreased cortical thickness and a decrease in the number and size of the trabeculae of cancellous bone (but normal chemical composition), resulting in increased fracture incidence. "Our BCL2 transgenic mice was also a useful tool to search the molecular targets of disuse osteoporosis, because we found that Pdk4 is responsible for bone loss at unloading by comparing the genes induced in wild-type mice and BCL2 transgenic mice at 4 months of age in the unloaded condition." (PMID 22768243, 2012). "In conclusion, osteoblast apoptosis is in part responsible for osteoporosis in sex steroid deficiency, glucocorticoid excess and aging, however, BCL2 inhibited osteoblast differentiation, impaired osteoblast function, and reduced the number of osteocyte processes." (PMID 22114675, 2011). "Bcl-2, a pivotal member of the Bcl-2 protein family, possesses all four Bcl-2 Homology (BH) domains that play a crucial role in inhibiting apoptosis in osteoporosis." (PMID 39834809, 2024). "The present study experimentally demonstrated the effect of Beclin-1/Bcl-2 on osteoblasts, which provided new ideas and theoretical basis for understanding the pathogenesis of osteoporosis." (PMID 39834809, 2024). "The Beclin-1/Bcl-2 complex plays a pivotal role in regulating both autophagy and apoptosis in osteoblasts affected by osteoporosis." (PMID 39834809, 2024). "In terms of bone and joint protection, the mechanisms of the protective effects on osteoporosis or osteoarticular disease involve regulation of the signaling of caspase-3/9, Bax/Bcl-2, PI3K/Akt/mTOR, Glo1-AGE-RAGE, AKT/Erk, and NF-κB signaling." (PMID 39301568, 2024). "The mRNA and protein levels of Bcl-2 in osteoclasts are distinctly increased in postmenopausal osteoporosis patients, leading to the inhibition of osteoclast apoptosis and excessive bone loss." (PMID 31546863, 2019). "Simultaneously, the mRNA expression of caspase-3, capase-9, RANKL was down-regulated and that of bcl-2 was up-regulated, which partially explains the anti-osteoporosis mechanism in MC3T3-E1 cells." (PMID 20966881, 2010). "Therefore, reducing the Beclin-1/Bcl-2 complex ratio in osteoblasts enhances autophagy and reduces apoptosis, which is a potential new option for the treatment of osteoporosis." (PMID 39834809, 2024). "However, there is limited research on the role of the Beclin-1/Bcl-2 complex in osteoblasts in the context of osteoporosis." (PMID 39834809, 2024).